MIR620 (microRNA 620)
Synonyms: hsa-mir-620; MIRN620
Gene: MicroRNA gene on chromosome 12 (116,148,560 to 116,148,654, reverse strand). Ensembl gene ENSG00000207967.
Diseases named in the same sentence as MIR620 in open-access papers:
MIR620 is named in the same sentence as 1 disease in open-access papers, as found by Europe PMC text mining. Sharing a sentence is not in itself a finding about the gene and the disease. The quoted sentences say what the papers report.
mental illnesses (1 paper, 2012). "This suggests that MIR620 could play an important role in the brain and potentially in the etiology of mental illnesses through dysregulation of numerous genes involved in the normal functioning of the brain." (PMID 22363459, 2012).